PLCB1 (phospholipase C beta 1)
Diseases named in the same sentence as PLCB1 in open-access papers (continued):
Sharing a sentence is not in itself a finding about the gene and the disease.
myelodysplastic syndrome (7 papers, 2020 to 2023). A clonal hematopoietic disorder characterized by dysplasia and ineffective hematopoiesis in one or more of the hematopoietic cell lines. "Notably, recent studies in myelodysplastic syndromes reported PLCβ1 mRNA as being correlated with favorable clinical outcomes, whereas decreased PLCβ1 expression was associated with poor prognosis." (PMID 35159043, 2022). "Moreover, it was already evidenced the role of PLCβ1 as possible molecular marker able to define specific and personal therapeutic strategies in other tumor patients, as myelodysplastic syndromes (MDS) patients." (PMID 35303162, 2022). "Interestingly, PLCβ1 is involved in haematological malignancies by regulating haematopoiesis, especially in Myelodysplastic Syndromes (MDS), where it acts on both erythropoiesis and myelopoiesis, with possible implications in transformation into AML." (PMID 34109125, 2021). "Interestingly, alterations in both PLCβ1 and PI3K/Akt/mTOR pathways have been associated with myelodysplastic syndromes (MDS) and acute myeloid leukemia (AML)." (PMID 32276377, 2020).
Obesity (7 papers, 2015 to 2025). Accumulation of substantial excess body fat. "Moreover, other DEGs involved in the protection of obesity, such as apolipoprotein C3 (O/C 7.66), phospholipase C beta 1 (O/C −8.55), and phospholipase A2, group IIF (O/C 3) were differentially expressed." (PMID 32899471, 2020). "Overall, a number of interesting genes that could play a role in obesity susceptibility have been identified within these CNVs (e.g. ASTN2, APOA2, PARK2, LINGO2, PLCB1, PTEN, and CIDEA)." (PMID 29441128, 2018). "In TNBC tumors of AA patients with obesity, seventeen miRNAs, seven of which (miR-195-5p, miR-130a-3p, miR-130a-5p, miR-424-5p, miR-148a-3p, miR-374-5p, and miR-30a-5p) potentially downregulated two or more genes (e.g., CLCN4, PLCB1, CDC25B, AEBP2, ERBB4)." (PMID 41009685, 2025).
bipolar disorder (6 papers, 2011 to 2024). A disorder of the brain that causes unusual shifts in mood, energy, activity levels and the ability to carry out day-to-day tasks. "The association of PLCB1 deletion and bipolar disorder appears much weaker assuming a valid initial diagnosis of BPD." (PMID 25566074, 2014). "PLCβ1 has been reported to be one of the first verifiable biomarkers that differentiate SZ from bipolar disorder." (PMID 39457654, 2024). "In a post-mortem brain study of 15 bipolar subjects bipolar disorder (BPD) a single deletion of PLCB1 was discovered in only one sample." (PMID 25566074, 2014).
colorectal cancer (6 papers, 2016 to 2024). A primary or metastatic malignant neoplasm that affects the colon or rectum. "Gene PLCB1 has been reported to be involved in the pathogenesis of neurological diseases and also as cancer-promoting in various tumors, including colorectal cancer." (PMID 38931955, 2024). "Hypomethylated PLCB1 was related to its increased expression in patients with colorectal cancer." (PMID 36875456, 2023). "CircFMN2/miR-1182 may also regulate the progression of colorectal cancer by targeting CD44, GNG7, RB1, COL1A2, PLCB1, SLC17A7, and TERT." (PMID 34249673, 2021).
hepatocellular carcinoma (6 papers, 2019 to 2025). A malignant tumor that arises from hepatocytes. "Upregulated expression of PLCB1 has been associated with the proliferation of tumor cells as well as in poor prognosis of hepatocellular carcinoma patients." (PMID 31080817, 2019). "Overexpression of Plcb1 has been correlated with advanced tumor stages and poorer survival outcomes in patients with breast, gastric cancers, and hepatocellular cancer, where it is thought to facilitate the migration and invasion of cancer cells." (PMID 40278994, 2025).
infantile epileptic encephalopathy (5 papers, 2014 to 2021). an epileptic condition characterized by epileptiform abnormalities associated with progressive cerebral dysfunction. "Previous studies on PLCB1 showed an association between its depletion and early-onset epileptic encephalopathy, suggesting its involvement in learning impairments and neurodegeneration." (PMID 29020091, 2017). "Autosomal recessive PLCB1-EIEE is an emerging cause of infantile epileptic encephalopathy, causing a number of different electroclinical phenotypes." (PMID 24684524, 2014). "Homozygous microdeletions of chromosome 20p12.3, disrupting the promoter region and first three coding exons of PLCB1, have previously been reported in two consanguineous families with early infantile epileptic encephalopathy." (PMID 25950944, 2015). "Homozygous deletions of chromosome 20p12.3, disrupting the promoter region and first three coding exons of the phospholipase C β1 gene (PLCB1), have previously been described in two reports of early infantile epileptic encephalopathy (EIEE)." (PMID 24684524, 2014).
cocaine dependence (4 papers, 2017 to 2022). A psychologically and socially impaired state, with or without physiological changes, that develops as a result of using cocaine and which leads to compulsive behaviors to acquire the substance. "PLCB1, Phospholipase C beta 1 protein, carry genetic variants associated with both cocaine dependence and drug dependence." (PMID 34453125, 2022). "We previously identified a genetic risk variant for cocaine addiction in the PLCB1 gene and found this gene upregulated in postmortem brains of cocaine abusers and in human dopaminergic neuron-like cells after an acute cocaine exposure." (PMID 34635637, 2021). "Here we studied the contribution of the PLCB1 gene to cocaine addiction and dissected its participation in the different aspects of the addictive process." (PMID 34635637, 2021). "Together with previous findings in humans and mice, PLCB1 merits to be further evaluated as a promising novel therapeutic target for preventing relapse and treating cocaine addiction." (PMID 34635637, 2021). "In the present work, we aimed to assess the contribution of the PLCB1 gene in the different stages of cocaine addiction using heterozygous KO mice (Plcb1+/−)." (PMID 34635637, 2021). "To conclude, we found that heterozygous deletion of the Plcb1 gene decreases cue-induced reinstatement of cocaine-seeking, pointing at PLCB1 as a possible therapeutic target for preventing relapse and treating cocaine addiction." (PMID 34635637, 2021). "Since we have shown that PLCB1 is involved in the vulnerability to cocaine dependence, we explored the possibility that its expression is altered by the action of cocaine." (PMID 28860459, 2017). "This study supports a role for PLCB1 in cocaine addiction, confirming previous findings in humans, and suggests it may be relevant in relapse to cocaine addiction." (PMID 34635637, 2021). "All this evidence suggest that PLCB1 may play a role in cocaine addiction." (PMID 34635637, 2021).
gastric cancer (4 papers, 2024 to 2025). A primary or metastatic malignant neoplasm involving the stomach. "PLCB1, recognized as an oncogene driving cancer progression, has been implicated in various cancers, including gastric cancer and cholangiocarcinoma." (PMID 41153425, 2025).
cardiac hypertrophy (3 papers, 2011 to 2025). "CTP‐miRNA106a, a first‐of‐a‐kind cardiac‐specific drug, downregulates genes involved in cardiac hypertrophy and inflammation through the PLCβ1 and CamKIIδ kinase pathways." (PMID 40820483, 2025).
coronary artery aneurysm (3 papers, 2015 to 2021). "rs6140791 polymorphism of the PLCB4 and PLCB1 genes might be involved in the pathogenesis of coronary artery aneurysm in Kawasaki disease." (PMID 34899595, 2021).
diabetes (3 papers, 2019 to 2024). "Then, we basically demonstrated that cinaciguat inhibited the PLCβ1 activation to attenuate the intracellular Ca2+ overload-ER stress pathway and protected the osteoblasts from diabetes." (PMID 34221234, 2021).
Anxiety (2 papers, 2015 to 2021). Intense feelings of nervousness, tension, or panic often arise in response to interpersonal stresses. "First, we performed a general phenotypic characterization and found that Plcb1+/− mice showed normal behavior, although they had increased anxiety and impaired short-term memory." (PMID 34635637, 2021). "Plcb1+/− showed increased anxiety in the elevated plus maze, reduced short-term memory in the novel object recognition paradigm, without any sign of depressive-like behavior in the anhedonia sucrose preference test." (PMID 34635637, 2021).
chronic obstructive pulmonary disease (2 papers, 2025). A chronic and progressive lung disorder characterized by the loss of elasticity of the bronchial tree and the air sacs, destruction of the air sacs wall, thickening of the bronchial wall, and mucous accumulation in the bronchial tree. "PLCB1 has also been associated with chronic obstructive pulmonary disease and endothelial cell inflammation." (PMID 40725399, 2025).
COVID-19 (2 papers, 2023 to 2025). A disease caused by infection with severe acute respiratory syndrome coronavirus 2. "PLCB1 is downregulated in patients with COVID-19 and was an enriched gene for inflammatory processes gene sets and is predicted to activate macrophages and B cells." (PMID 40725399, 2025). "The expression of PLCβ1 and PLCβ2 was increased and downregulated, respectively, in GCs-treated COVID-19 patients." (PMID 36851787, 2023).
drug dependence (2 papers, 2017 to 2022). "We found an association between rs1047383 in the PLCB1 gene and drug dependence that was replicated in an independent sample (663 cases and 667 controls)." (PMID 28860459, 2017).
endothelial dysfunction (2 papers, 2015 to 2016). In vascular diseases, endothelial dysfunction is a systemic pathological state of the endothelium (the inner lining of blood vessels) and can be broadly defined as an imbalance between vasodilating and vasoconstricting substances produced by (or acting on) the endothelium. "This is the first study to report that PLCB1 is a regulator of vascular inflammation and thus its use might be beneficial for many inflammatory diseases associated with endothelial dysfunction." (PMID 26434682, 2015). "This is the first study to report that PLCB1 is a regulator of vascular inflammation and to suggest that its use might therefore be beneficial for the management of inflammatory diseases associated with endothelial dysfunction." (PMID 26434682, 2015). "The critical role of PLCβ1 in mediating endothelial dysfunction is supported by the data that knockdown of PLCβ1 in Zdhhc21+/+ ECs led to a significantly attenuated TER response to thrombin." (PMID 27653213, 2016). "Moreover, comparisons were made in endothelial cells subjected to PLCβ1 knockdown, PLCβ1 wild-type overexpression and PLCβ1 C17 mutant overexpression to determine the mechanistic contribution of PLCβ1 to endothelial dysfunction." (PMID 27653213, 2016).
Epileptic encephalopathy (2 papers, 2022 to 2025). A condition in which epileptiform abnormalities are believed to contribute to the progressive disturbance in cerebral function. "Mutations in the PLCB1 gene have been associated with epileptic encephalopathy and West syndrome." (PMID 40278994, 2025).
infertile (2 papers, 2022 to 2023). "Further, PLCB1 disruption resulted in infertile mice with pleiotropic reproductive defects." (PMID 35774501, 2022).
lung cancer (2 papers, 2011 to 2024). A malignant neoplasm involving the lung. "The activation of PLCB1 is an early and common response to stimulation of G protein-coupled receptors by these neuroendocrine growth factors and has been used for diagnostic and therapeutic target in lung cancer and multiple blood diseases." (PMID 21645413, 2011).
melanoma (2 papers, 2020 to 2021). A malignant, usually aggressive tumor composed of atypical, neoplastic melanocytes. "PLCB1 was chosen among its different isoforms as it is upregulated in melanoma metastasis." (PMID 33082334, 2020). "In addition, PLCB1 is activated by G-protein-coupled receptors (GPCRs), whose expression is one of the top-ranked protein classes associated with the resistance to MEK inhibitors in melanoma." (PMID 34064422, 2021). "It is possible that HDAC8 induces PLCB1 through deacetylating/activating c-JUN, as in the BRAF inhibitor-resistant melanoma." (PMID 34064422, 2021).
myotonic dystrophies (2 papers, 2022 to 2023). "Furthermore, some of the Wnt signaling genes, such as Phosphoinositide-phospholipase C β1 (PLCβ1), are reported to play a crucial role in initiating the genetic program responsible for muscle differentiation and have been correlated with myotonic dystrophies." (PMID 36980840, 2023).
Nausea (2 papers, 2016 to 2021). A sensation of unease in the stomach together with an urge to vomit. "With a minimal amount of initial odor-sugar associative training, both PLCβ1+/+ and PLCβ1-/- mice were able to form an aversion to the sugar reward when the odor CS predicting sugar was paired with nausea." (PMID 26731530, 2016). "With a minimal amount of initial +odor→sugar associative training (1S*3Days), both wild-type and PLCβ1-/- mice established an aversion to the sugar reward when the odor cue predicting sugar (+odor) was paired with nausea." (PMID 26731530, 2016). "With a “minimal” amount of initial odor-sugar training (one training session a day for 3 days: 3Days), both the WT and PLCβ1-KO mice were able to form an aversion to sugar when the odor CS predicting sugar was paired with LiCl-induced nausea." (PMID 34899203, 2021).
neuroblastoma (2 papers, 2016 to 2024). Neuroblastoma (NB) is the most common solid, extracranial childhood tumor. "Control of neuronal cell differentiation by agents based on PLCβ1 here may have impact for treatments for neuroblastomas and diseases associated with neuronal de-differentiation." (PMID 38789419, 2024).
Parkinson (2 papers, 2019 to 2020). "We also found that GNAQ, GRIN1, and PLCB1 are in both Huntington's and AD but not in Parkinson's pathways, and SNCA is in both Parkinson's and AD but not Huntington's pathways." (PMID 31068785, 2019).
Sepsis (2 papers, 2021 to 2022). Sepsis is defined as life-threatening organ dysfunction caused by a dysregulated host response to infection. "Among 5,607 DEGs, Lrg1, Ace2, Itgb6, Hmgb2, Pik3r5, Itgam, Plcb1, Jak2, Vegfa, and Hif1α were associated with the entire course of sepsis-induced myocardial injury, which have been reported previously." (PMID 35721566, 2022). "Artificial intelligence systems identified eight out of twenty novel genetic markers (SDC4, CLEC5A, TCN1, MS4A3, HCAR3, OLAH, PLCB1, and NLRP1) that help predict sepsis severity or mortality." (PMID 33692779, 2021).
type 2 diabetes (2 papers, 2021 to 2022). "T C Zhou showed that PLCB1 regulates the energy or glucose homeostasis in the development of type 2 diabetes in one family." (PMID 34609028, 2021).
acute lymphoblastic leukemia (1 paper, 2022). Leukemia with an acute onset, characterized by the presence of lymphoblasts in the bone marrow and the peripheral blood. "In acute lymphoblastic leukemia (ALL) cells, STIM1‐dependent Ca2+ entry has been linked to PKCβ2 activation and in vascular smooth muscle cells (VSMCs) STIM1 has been linked to increased PLCβ1 activity and subsequent phosphorylation of PKC." (PMID 35179826, 2022).
acute pancreatitis (1 paper, 2022). An acute inflammatory process that leads to necrosis of the pancreatic parenchyma. "AR42J cells and HPDE6-C7 cells were transfected with an overexpression of plasmids or shRNA to investigate the effects of the SNHG11/miR-7-5p/PLCB1 axis on cell proliferation and apoptosis, inflammatory cytokine secretion, and acute pancreatitis." (PMID 36611865, 2022). "More importantly, our conclusions indicate that SNHG11 and PLCB1 genes may not only be involved in acute pancreatitis and also be one of the important targets of other inflammations in the body, which deserves more exploration on the role of SNHG11 and PLCB1 genes in the disease in the future." (PMID 36611865, 2022). "The reduction of this lncRNA will further reduce the adsorption of miR-7-5p, make miR-7-5p bind a large amount of downstream protein PLCB1, reduce its expression, enhance the P38MAPK signaling pathway, form a cascade effect, and promote the progression of acute pancreatitis." (PMID 36611865, 2022).
African trypanosomiasis (1 paper, 2019). "More so, three unique Muturu candidate genes, namely FAS, IDO2, and PLCB1, are part of the candidate African trypanosomiasis KEGG pathway (BTA05143) revealed following functional annotation terms by DAVID bioinformatic tool." (PMID 31231417, 2019).
amyloidosis (1 paper, 2021). A disorder characterized by the localized or diffuse accumulation of amyloid protein in various anatomic sites. "Our results are the first to show that increasing PLCβ1 activity via m-3M3FBS application rescues hippocampal tLTP induction and contextual fear memory impaired by amyloidosis, possibly by restoring S-eCB mobilization." (PMID 34625112, 2021).
astrocytomas (1 paper, 2016). "When PLCβ1 expression is stratified by 3X downregulation in astrocytoma cases, the survival curve is still significantly different in the intermediate group compared to the downregulated PLCβ1 groups (p = 0.018)." (PMID 26614510, 2016). "Confirming this observation, our data analysis showed that PLCβ1 signal in oligodendroglioma is significantly higher than that in pooled data of astrocytomas." (PMID 26614510, 2016). "The results that average PLCβ1 expression in grade III (n = 19) is significantly higher than in grade IV (n = 81) astrocytoma (p = 0.044) is consistent with previous analysis." (PMID 26614510, 2016). "Average PLCβ1 levels from normal tissue controls are significantly higher than those from low-grade tumors and its level is further downregulated in higher grade tumors, including astrocytomas and oligodendrogliomas in GDS1962." (PMID 26614510, 2016). "Furthermore, overall oligodendroglioma samples (n = 50) showed significantly higher levels of PLCβ1 than astrocytomas (n = 107, p = 1.4E-6)." (PMID 26614510, 2016). "A cellular study also demonstrated that PLCβ1 expression levels in oligodendrocytes were higher than that in astrocytes, a finding that may be useful in interpreting the clinical outcome whereby oligodendroglioma patients usually have a better prognosis than astrocytoma patients." (PMID 26614510, 2016). "The average PLCβ1 expression in nontumor controls (n = 23) is also significantly higher than in pooled data of all astrocytoma cases (n = 107, p = 9.6E-9)." (PMID 26614510, 2016).
Ataxia (1 paper, 2021). Ataxia refers to impaired coordination of voluntary muscle movement. "Plcb4–/– mutant mice exhibited cerebellar hypoplasia and ataxia, closely mirroring neuronal phenotypes associated with IPTR1 mutations, indicating a functional connection between IPTR1 and PLCB1." (PMID 33747042, 2021).
atrial fibrillation (1 paper, 2024). A disorder characterized by an electrocardiographic finding of a supraventricular arrhythmia characterized by the replacement of consistent P waves by rapid oscillations or fibrillatory waves that vary in size, shape and timing and are accompanied by an irregular ventricular response. "MiR-26 can also suppress atrial fibrillation (AF) and cardiomyocyte hypertrophy by targeting β-MHC, GSK3β, GATA4, KCNJ2, and PLCβ1." (PMID 38195542, 2024).
bladder cancer (1 paper, 2020). "To better understand the role of ECs and NAEs in bladder cancer, we analyzed gene expression data from TGCA database regarding the metabolic pathway of the ECS, comprising the synthetic enzymes (PLCB1-4, PTPN22, ABHD4, GDE1, DAGLA, DAGLB, and NAPE-PLD) and the hydrolytic ones (FAAH, NAAA, and MGLL)." (PMID 32260109, 2020).
brain tumors (1 paper, 2016). "In addition, the REMBRANDT database only stratifies brain tumors as PLCβ1 “intermediate” and “downregulated” groups, in contrast to most of the other genes, which usually present as bidirectional changes." (PMID 26614510, 2016).